HMGB1 (high mobility group box 1)
Diseases named in the same sentence as HMGB1 in open-access papers (continued):
Sharing a sentence is not in itself a finding about the gene and the disease.
infection (continued). "Interestingly, the increase in plasma HMGB1 levels was associated with the decrease in HLA-DR expression and, importantly, with the development of postoperative infections, suggestive of a dominant role for this DAMP." (PMID 29675023, 2018). "In addition, necrosis of host cells due to the infection will also provide more ligands (such as actin and HMGB1) to activate TREM-1 signaling to cause severe inflammation." (PMID 29619033, 2018). "Anti-HMGB1 pAb-treated septic mice had a survival advantage compared to control mice following secondary infection and treatment was associated with improved antimicrobial responses as mice exhibited increased IL-12 and decreased IL-6 following infection." (PMID 28724977, 2017). "Interestingly, patients with severe PUUV infection had the highest concentration of HMGB1, although infection with DOBV and CCHFV usually causes more severe hemorrhagic manifestations." (PMID 27348219, 2016). "Activation of the IL-1R/TLR pathway may be due to brain injury or infection, but could also be caused by DAMPs, such as HMGB1." (PMID 24265605, 2013). "HMGB1, a highly conserved, ubiquitous protein that presents in the nuclei and cytoplasm of nearly all cell types, is a necessary and sufficient mediator of inflammation during sterile- and infection-associated responses." (PMID 23554835, 2013). "Based on this tissue distribution, we speculate that IL-33 may function as an endogenous ‘alarmin’, similarly to chromatin-associated cytokine HMGB1, to alert the immune system of tissue injury or infection." (PMID 18836528, 2008). "For example, inhibition of HMGB1 may not only impede wound healing and compromise tissue regeneration but also disrupt immune-mediated pathogen clearance, thereby augmenting susceptibility to infections." (PMID 40877572, 2025). "In addition, a mild infection may activate the IL-1 receptor–toll-like receptor pathway; however, damage-associated molecular patterns including high mobility group box 1 could engender such activation." (PMID 29796346, 2018). "In addition, fip200 deficiency significantly decreased mRNA level of HMGB1 upon PAO1 infection." (PMID 24923305, 2014). "In contrast, the infection with Salmonella significantly upregulated levels of all observed inflammatory cytokines and HMGB1, except for IFN‐γ." (PMID 41474380, 2026). "Levels of inflammatory cytokines IL‐1β, IL‐6, IL‐8, IL‐10, IL‐12/23p40, TNF‐α, and HMGB1 were significantly upregulated by infection with S. Typhimurium in the LT2 group." (PMID 41474380, 2026). "While IL‐1β, TNF‐α, and IL‐6 exhibited a declining trend following the initial peak within 72 h, implying potential resolution of the initial infection, the trajectory of HMGB1 levels remained inconspicuous and even continued to rise in the spleen until 72 h." (PMID 41551210, 2026). "Our results showed that during infection, HMGB1 levels decreased because the virus suppressed its production." (PMID 40919947, 2025). "The HMGB1 mRNA and protein levels in the spleen were increased in the infection group compared with the control group (p < 0.001)." (PMID 40305201, 2025). "Treatment with 1 and 0.5 mg/mL S-PN resulted in a significant reduction in HMGB1 level in the MRSA-PMN system post-infection, compared to the untreated Model (MRSA-PMN) group (P < 0.05)." (PMID 40520183, 2025). "We found significant elevations in two of these three DAMPs, calreticulin and HMGB-1, following infection of all our SS cell lines with MV-s-NAP." (PMID 41235176, 2025). "During HAdV-C5 infection, HMGB-1 became re-localized to numerous nuclear regions with more densely grouped small foci." (PMID 39611842, 2025). "Immunoblot analyses of both subnuclear fractions and whole cell lysates at the same time points confirmed both an enrichment of HMGB1 in RCs and an overall decrease during the progression of HAdV-C5 infection." (PMID 39611842, 2025).
infection (continued). "HMGB1 is an alarmin expressed during infection, an intermediate in innate immune responses to bacterial DNA, and a marker of severe SARS-CoV-2 infection." (PMID 40367285, 2025). "The HMGB1 protein appeared to decrease significantly in concentration by 36 hpi, suggesting that HAdV-C5 infection induces degradation of this protein." (PMID 39611842, 2025). "In A549 cells, HAdV-C5 protein VII was shown to bind HMGB1 to repress innate immune responses and promote infection." (PMID 40367285, 2025). "At an MOI of 1:10 and an infection duration of 4 h, the levels of HMGB1 were elevated to a greater extent compared to MOIs of 1:5 or 1:20, or infection durations of 1 h or 18 h." (PMID 40520183, 2025). "In this study, we aimed to better understand the role of HMGB1 in the infection process of a human DNA virus, HAdV-C5." (PMID 40919947, 2025). "The HMGB1 mRNA and protein levels were decreased in the Pro10, Pro20, Pro40, Amo20, Pro20 + Amo20, and Bai100 groups compared with the infection group (p < 0.05)." (PMID 40305201, 2025). "To confirm the effect of HMGB1 on HAdV-C5 infection, we transduced A549 cells with either scrambled (scr) or shHMGB1 and measured viral DNA and virus yield." (PMID 39611842, 2025). "To determine the molecular pathway of HMGB1 secretion in corneal epithelial cells, we further examined HMGB1 intracellular trafficking upon infection." (PMID 40367285, 2025). "Overall, our findings highlight how HMGB1 plays a crucial role in facilitating efficient virus replication, making it an important factor in the infection process." (PMID 40919947, 2025). "Reduced HMGB1 primarily has chemotactic activity to attract immune cells to sites of injury or infection." (PMID 40308590, 2025). "Facsimile supernatants showed an increase of secreted HMGB1 upon infection, and this was reduced with FSSE pretreatment." (PMID 40367285, 2025). "High mobility group box 1 (HMGB1) is another factor whose expression is induced by infection, and HMGB1-mediated autophagy is dispensable for EVA71 replication in several cell populations." (PMID 40869312, 2025). "The results above indicate a dynamic process for HMGB1 secretion by corneal epithelial cells upon infection with adenovirus." (PMID 40367285, 2025). "Densitometry of the HMGB1 band on Western blots confirmed HMGB1 translocation from the nucleus to the cytoplasm to the extracellular space in a time dependent fashion upon infection, seen only in THE and PCEC." (PMID 40367285, 2025). "In contrast to HAdV-C5 infection, the concentrations of HMGB1 in the cell culture supernatant showed an increase during the later stages of infection in HAdV-B7-infected A549 cells, where HMGB1 activated the immune response." (PMID 39611842, 2025). "Analysis of relative fluorescence for cytoplasmic HMGB1 at each time point after infection as compared to mock infection was consistent with the movement of HMGB1 into the cytoplasm and then into the cell supernatant." (PMID 40367285, 2025). "High-mobility group box 1 (HMGB1), a DNA-binding protein, is abundantly expressed in the nucleus and regulates the immune response intracellularly and extracellularly upon infection." (PMID 39927458, 2025). "For instance, in oral diseases, infection with Porphyromonas gingivalis in patients with periodontitis induces the release of HMGB1 from host cells, which promotes osteoclastogenesis, leading to periodontal tissue destruction and bone resorption." (PMID 40877572, 2025). "There is evidence that HMGB1 is critically important for both triggering and resolving inflammation, which follows infection or trauma." (PMID 39682740, 2024). "In chickens, the inflammatory factors HMGB1 and IL-6 are widely expressed in the lungs after Pm infection." (PMID 39850582, 2024). "Triggered by microbial products like LPS, infections or endogenous host stimuli, active HMGB1 extracellular secretion occurs via intracellular vesicles." (PMID 39008169, 2024).
infection (continued). "Levels of extracellular ATP and HMGB1 were analyzed using the CM of NHOS cells 24 h after infection." (PMID 39108499, 2024). "Infection with PRRSV promotes the release of high mobility group box 1 (HMGB1), a mediator of inflammatory responses in pulmonary damage caused by PRRSV-induced infection." (PMID 39766272, 2024). "OBP-702 infection induced an increase in ATP release, upregulation of calreticulin expression on the surface of GC cells, and intracellular HMGB-1 expression." (PMID 38745748, 2024). "HMGB1 (High mobility group box-1 protein) is an important factor involved in mediating infection, tissue damage, and inflammation, and is present at extremely low levels in the serum of healthy individuals." (PMID 39512354, 2024). "Extracellularly released HMGB1 is a weapon in the fight against infection through proinflammatory response and immune regulation." (PMID 39046369, 2024). "HMGB1 is actively secreted by macrophages and other cells or after infection and release from damaged/necrotic cells." (PMID 39445002, 2024). "Contrary to HMGB1, extracellular release of ATP was triggered by the virus twenty-four to seventy-two hours after infection in all CTCL cell lines." (PMID 39123440, 2024). "Compared with the control group, the Pm challenge group showed significantly increased PARP1, HMGB1, IL-1β, and IL-18 protein expression in the blood vessels, indicating that Pm infection in mice triggered vascular inflammatory injury." (PMID 39850582, 2024). "The levels of extracellular ATP and HMGB1 were analyzed using CM of human OS cells 24 h after infection." (PMID 39108499, 2024). "lactis BB-12 (BB12) decreased HMGB1 levels and partly ameliorated inflammatory responses following infection with the Salmonella Typhimurium strain LT232." (PMID 38172612, 2024). "The fluorescein staining indicated the extent of cornea damage and the serum level of HMGB1 was applied as an indicator for the severity of infection." (PMID 38628549, 2024). "Pretreating animals with UP446 showed a 71.6% reduction in the level of HMGB1 expression compared to vehicle-treated mice exposed to hyperoxia and PA infection." (PMID 37764336, 2023). "It has been found that HMGB1 functions as a critical regulator in OS-related infection, sterile inflammation, necrosis, and apoptosis." (PMID 37863934, 2023). "Eventually, exacerbated infection with CV-B5/F resulted in the release of HMGB1 from the nucleus into the cytosol and supernatant." (PMID 37743418, 2023). "We observed a significant enrichment of RAGE and Rap signaling pathways, which are downstream of HMGB1 signaling following infection." (PMID 36789106, 2023). "Instead, the pattern more resembled that of endogenous HMGB1 upon infection with a protein VII-null virus." (PMID 37703278, 2023). "Following tissue injury or infection, HMGB1 is indeed released by necrotic cells, activated immune cells, or as a component of NETs." (PMID 36829432, 2023). "High-mobility group box 1 protein (HMGB1) was discovered to be a crucial cytokine that mediates the response to infection, injury, and inflammation." (PMID 38001807, 2023). "High-mobility group box protein 1 (HMGB1), a signal of tissue damage, recruits mononuclear cells to sites of tissue damage to protect against possible infection." (PMID 36916913, 2023). "HMGB1, released in small amounts during infection, can mediate disease by activating innate immunity through activities that contribute to inflammatory responses that can be remediated." (PMID 37685970, 2023). "A recent study revealed that RSV infection of hAECs induces the biphasic release of HMGB1 at 6 (“early”) and 24 (“late”) hours post-infection." (PMID 37798799, 2023). "They suggest that HMGB1 activates the immune response after injury or infection by stimulating the release of cytokines and the activation of immune cells." (PMID 37325273, 2023).
infection (continued). "As an immune protein released during tissue damage, infection, or inflammation, HMGB1 plays a crucial role in regulating innate and adaptive immune responses." (PMID 37520371, 2023). "This notion is consistent with insolubility as a proxy for HMGB1 release affecting systemic inflammatory responses to infection." (PMID 37703278, 2023). "Together, our results demonstrate that protein VII specifically harnesses HMGB1 through its A-box domain to depress the innate immune response and promote infection." (PMID 37703278, 2023). "We quantified these localization patterns and conclude that the A-box is required for protein VII to render HMGB1 bound to the chromatin during infection." (PMID 37703278, 2023). "With infection, injury and sterile inflammation, HMGB1 is passively released from damaged cells or actively secreted from activated immune cells." (PMID 37628850, 2023). "More importantly, the administration of HMGB1 inhibitor after severe infection can significantly reduce the relevant inflammatory response after changing its mRNA expression." (PMID 38156383, 2023). "During infection or injury, activated immune cells and damaged cells release HMGB1 into the extracellular space, where HMGB1 functions as a pro-inflammatory mediator and plays an important role in the pathogenesis of inflammatory diseases." (PMID 37628850, 2023). "The part of GN piglets infected with necrotoxigenic E. coli O55 that relatively thrived showed low levels of plasmatic and intestinal HMGB1, but the piglets that suffered from the infection showed highly increased levels." (PMID 36768650, 2023). "HMGB1 also acts as a late mediator of infection-driven inflammation, such as during sepsis, where it is secreted by activated macrophages and monocytes exposed to pathogens in a later time window than other cytokines." (PMID 36829432, 2023). "Taken together, these results indicate that during infection protein VII binds the A-box of HMGB1, rendering it insoluble and sequestered in chromatin." (PMID 37703278, 2023). "In contrast, during infection we find that full length HMGB1, A-box only, and AB-box, that is constructs containing the A-box, are insoluble whereas the B-box alone and BC-tail constructs are soluble (lane 6)." (PMID 37703278, 2023). "Pretreating animals with UP446 showed a 71.6% reduction in the level of extracellular HMGB1 in the lung lavage compared to vehicle-treated mice exposed to hyperoxia and PA infection." (PMID 37764336, 2023). "Several studies have demonstrated that endogenous stimuli, exogenous microbial products, and infections with various pathogens can induce active secretion of HMGB1 by immune cells, endothelial cells, epithelial cells, fibroblasts, or other cells." (PMID 37667233, 2023). "HMGB1 is present in the nucleus and cytoplasm of cells, and is released from cells during infection and sterile tissue injury." (PMID 36658496, 2023). "Damage-associated molecular patterns (DAMPs) are immune-activating proteins that are secreted after cell injury or infection and include interleukins, heat-shock proteins, high-mobility group box 1 (HMGB1), and S100 proteins." (PMID 37175422, 2023). "The released extracellular HMGB1, a key damage-associated molecular pattern (DAMP) molecule, is the central mediator of lethal inflammation in tissue damage or infection." (PMID 35294955, 2022). "We observed that the levels of HMGB1 in LysmCreHdac3f/f mice were higher than those in LysmCre mice after infection." (PMID 35658939, 2022). "A recent study showed that infection of A549 cells with DENV-2 for 24 h (MOI of 5) induced HMGB1 accumulation in the cytoplasm and its subsequent release." (PMID 36016387, 2022). "This C188-9 pre-treatment, followed by NDV/FMW infection, profoundly enhanced HMGB1 and HSP70/90 release and increased CRT exposure." (PMID 36755812, 2022).
infection (continued). "Inhibition of HMGB1 release reduces the number of autolysosomes and “autophagic flux” in human and mouse cell lines under oxidative stress such as infection condition, and traumatic or injury." (PMID 35340325, 2022). "It was demonstrated that MG infection triggered the release of HMGB1 and accelerated its infection progression." (PMID 36139393, 2022). "Our data indicated that ORFV NA1/11 infection triggered the apoptosis of lung cancer cells and inhibited the growth of implanted lung tumors in mice by enhanced release of HMGB1, ATP and CXCL16 secretion to promote DCs activation and recruit CD8 T cells." (PMID 35959371, 2022). "The expression of HMGB-1 in bovine endometrial explants was reduced by PGD2 inhibitors after infection." (PMID 36435808, 2022). "HMGB1 levels were compared with inflammation and infection in a pooled analysis of all available data for all patients during treatment." (PMID 34671818, 2022). "Here, we show that RSV infection of hAECs induces the biphasic release of HMGB1 at 6 (“early”) and 24 (“late”) hours post infection (hpi)." (PMID 35712662, 2022). "HMGB1 expression was enhanced in humphead snapper and grass carp during the infection of Vibrio harveyi and grass carp reovirus, respectively." (PMID 36140677, 2022). "In response to infection and tissue damage, HMGB1 can be actively secreted and passively released outside cells, where they function as damage-associated molecular pattern molecules (DAMPs) to mediate inflammation and immune responses." (PMID 35217834, 2022). "Twenty-four hours after infection, nucleus, plasma, and membrane of HD-11 were isolated and HMGB1 expression was assayed individually in these cellular fractions." (PMID 36139393, 2022). "Numerous studies have shown that HMGB1 participates in the replication and infection process of pathogens." (PMID 36139393, 2022). "In comparison with the control cells, ORFV NA1/11 infection increased in the release of the nuclear HMGB1, evident by the increased protein levels of HMGB1 in the cytoplasm of A549 and LLC cells in a trend of time-dependent." (PMID 35959371, 2022). "In contrast, the RAGE agonist HMGB1 was significantly elevated in the lungs on day 4 after infection relative to the appropriate uninfected control." (PMID 35076028, 2022). "At time points with infections, mean HMGB1 levels were also significantly higher than in samples taken without simultaneous infections (p = 0.002)." (PMID 34671818, 2022). "Consistently, the presence of HMGB1 reduced the infection of P. fluorescens to PBLs, most likely as a result of an augmented inflammatory response, phagocytosis, and ROS killing elicited by HMGB1." (PMID 36140677, 2022). "Recently, a study showed that serum HMGB1 levels had a high correlation with infection and a moderate correlation with AKI and death." (PMID 36712653, 2022). "Infection accompanied by the release of HMGB1 contributes to circulatory dysfunction and is one of the major contributing factors of AKI." (PMID 36712653, 2022). "HMGB1 and SQSTM1 are potential therapeutic targets for infection as well as sterile inflammation caused by tissue damage." (PMID 35769880, 2022). "Since HMGB1 was found to be elevated in inflammatory and infectious diseases as well, we recorded corresponding CRP levels (n = 61) and data on infections (n = 53) and treatment-associated toxicity (n = 58) during therapy." (PMID 34671818, 2022). "The extracellular HMGB1 level was elevated in a time- and multiplicity of infection (MOI)-dependent manner." (PMID 35058496, 2022). "HMGB1 is a nuclear transcription factor that acts as a pro-inflammatory cytokine when released from the cells in response to infection, cell injury and inflammation." (PMID 35058496, 2022).